KRAS (KRas proto-oncogene, GTPase)
Diseases named in the same sentence as KRAS in open-access papers (continued):
Sharing a sentence is not in itself a finding about the gene and the disease.
tumor (continued). "How KRAS mutations are involved in the tumor immune microenvironment and in the sensitivity/resistance of ICI is currently the focus of research." (PMID 39080202, 2024). "SRC inhibitors (DGY-06-116, dasatinib, and bosutinib) also exhibit synergistic effects with MRTX849 in eliminating various tumor cell lines carrying KRAS-G12C mutations." (PMID 39661665, 2024). "The up-regulation of CDKN2A in CRC tissue and the interaction with the KRAS mutation status (meaning more up-regulation in the presence of mutation) remained significant even when the tumor stage was taken into account." (PMID 39125664, 2024). "Although co-mutations in several genes have prognostic relevance in KRAS-mutated patients, their effect on tumor immunogenicity are poorly understood." (PMID 39113608, 2024). "Tumor grade displayed a statistically significant relationship with KRAS mutations (p-value = 0.043), with well-differentiated tumors exhibiting fewer mutations compared to moderate and undifferentiated tumors." (PMID 38465160, 2024). "Even then, further research is required to verify if the radiologically observed skewness is responsible for poor local control by affecting the tumor density and texture or if skewness is only a biomarker of KRAS mutations." (PMID 39816274, 2024). "Recent research has highlighted the pivotal role of the ERK pathway in KRAS-mutated cell lines, revealing that its activation is crucial for tumor growth and survival, whereas the MAP pathway appears to be less significant." (PMID 39001391, 2024). "In conclusion, we designed and constructed a DNA/γPNA hybrid nanoreporter that can specifically recognize and record KRAS(G12D) mutation in peripheral blood, allowing for urinary monitoring of tumor‐associated DNA mutation via γPNA urinalysis." (PMID 38958527, 2024). "Mitophagy, a selective autophagy of mitochondria driven by KRAS mutations, reduces the amount of functional mitochondria, showing its crucial role in redox robustness and tumor formation." (PMID 39682280, 2024). "While KRAS-mutated tumours displayed decreased immune cell infiltration compared to KRAS wild-type tumours, the opposite was found for BRAF-mutated tumours, differences that were most obvious for the cytotoxic T cells and the Th1 cells." (PMID 38040818, 2024). "According to the authors, activated KRAS serves as the initiator of the premalignant lesion, while the p16 tumor suppressor loss determines the malignant conversion into invasive ductal adenocarcinoma." (PMID 38607041, 2024). "The ablation of the KRAS mutant or GC1 reduced tumor-sphere formation capacity, suggesting a loss of cancer cell stemness." (PMID 39795950, 2024). "Given the low number of organoids, representing limited heterogeneity in tumour subtypes, or even KRAS mutations, it is indeed difficult to extrapolate our findings to a larger scale." (PMID 39516561, 2024). "KRAS mutations are among the earliest events in pancreatic carcinogenesis and can drive common metabolic programs and promote tumour progression." (PMID 39090116, 2024). "Pearson correlations revealed a negative association between KRAS levels and miR-877-5p levels in the 56 paired tumor and control tissue samples, while a positive association was observed between KRAS levels and circ_0039787 levels." (PMID 38309290, 2024). "These mutations confer constitutive activation of KRAS signaling pathways, driving tumorigenesis, tumor growth, survival, metastasis, and therapeutic resistance." (PMID 39456549, 2024).
tumor (continued). "Polyclonal tumours retain a structure comprising subclones with distinct Apc mutations and transcriptional states, driven predominantly by differences in KRAS and MYC signalling." (PMID 39478206, 2024). "Though the individual mutation of APC and KRAS influences tumor growth and survival, the severity of CRC significantly rises when there are both mutations in the cell." (PMID 39056802, 2024). "While the genetic landscape described in tumor tissue was consistent to what had been previously reported (87.5% of patients presented pathogenic alterations, mostly variants in KRAS (81.3%), plasma ctDNA results only partially covered this scenario." (PMID 39003322, 2024). "The effectiveness of using KRAS mutation status from the primary tumor alone to predict response to anti-EGFR agents remains a subject of ongoing debate." (PMID 39064004, 2024). "If oncogenic KRAS mutations contribute to aneuploidy tolerance, we would predict that KRAS mutant tumor cell lines have higher aneuploidy levels as they should be more tolerant." (PMID 39294502, 2024). "Recent data demonstrate that gain-of-function KRAS mutations lead to extensive remodeling of the tumor immune microenvironment in several tumor types." (PMID 39113608, 2024). "The proportion of KRAS mutated tumours was found to decrease with increasing score of infiltrating cytotoxic T cells, while the proportion of BRAF mutated tumours instead was found to increase." (PMID 38040818, 2024). "This study investigatedthe therapeutic effect of PAL toward KRAS-mutatedCRC cell lines and the use of MB and US to enhance localized deliveryto tumor cells." (PMID 39554410, 2024). "In contrast, another study identified Il33 as a main target of the gene regulatory programs that allow the “acinar-to-neoplasia” switch and the initiation of PC in the context of KRAS mutations." (PMID 38942797, 2024). "Most notably, BFB-associated sequences decreased between the tumor biopsy and across organoid passages, while ecDNA-associated sequences (e25) containing KRAS and correlated sequences increased." (PMID 38744814, 2024). "In this study, we focused on an LGSOC with a KRAS mutation from which several well-characterized patient-derived tumor models are established, generated from peritoneal metastases, including a patient-derived cell line, mouse PDX and long-term 3D scaffold." (PMID 38791891, 2024). "This study aimed to validate a technique that combines the amplification refractory mutation system (ARMS) with high-resolution melting analysis (HRMA) for detecting mutations in codon 12 of KRAS in tumor and plasma, and to assess its prognostic value." (PMID 39456638, 2024). "KRAS mutations were more common in patients with longer tumor long diameters than in patients with shorter tumor long diameters (P = 0.006)." (PMID 39364008, 2024). "Initiation of the serrated neoplasia pathway typically involves genetic mutations in the BRAF or KRAS genes, followed by tumor suppressor gene methylation known as CpG island methylator phenotype (CIMP)." (PMID 39113889, 2024). "For instance, the invasive subgroup triggers a response to hypoxia, KRAS, and matrix remodeling pathways, typically associated with tumor cells deprived of oxygen." (PMID 39456679, 2024). "Oncogenic events such as KRAS mutations have also been implicated in suppressing or evading anti-tumor immune responses through immune checkpoint molecules." (PMID 39539964, 2024). "In this study, KRAS was the gene in which high- or moderate-impact variants most strongly differentiated BOT from all the other tumor groups, except lgOvCa." (PMID 39456660, 2024). "Overall, the presence of KRAS mutations in cancer cells can promote angiogenesis, which can lead to aggressive tumor growth and progression." (PMID 38481800, 2024).
tumor (continued). "Different biological samples, including fresh and fixed tumor tissue or biopsy samples, fine-needle aspiration materials and cytological samples, total blood, and plasma, can be used to detect KRAS mutation." (PMID 39767746, 2024). "A phase I study including patients with solid tumors harboring any missense mutation at KRAS G12 showed promising anti-tumor activity with reasonable safety." (PMID 38756650, 2024). "Integrated cell phenotypes revealed that KRAS mutation and KRASiGD were related to epithelial-tumor mesenchymal transformation and dedifferentiation degrees." (PMID 39839479, 2024). "To examine the in vitro binding of HLA-G12V/CD3 BiTE, we chose five kinds of tumor cells with different KRAS mutations." (PMID 38752985, 2024). "Specifically, positive mutant KRAS–ctDNA status has been associated with earlier tumour recurrence, greater metastatic burden, and shorter median progression-free survival (mPFS) and median overall survival (mOS)." (PMID 39409954, 2024). "This compound exhibited higher selectivity and lower unspecific cytotoxicity, displaying strong potential for targeting KRAS-mutated tumor cells." (PMID 39125664, 2024). "Several resistance mechanisms have been already described, ranging from new mutations in the KRAS gene to the rewiring of the tumor cells’ signalization network." (PMID 39687047, 2024). "In this study, we generated HLA-G12V/CD3 BiTE, a bispecific antibody that can specifically target T cells and HLA-A2 positive tumor cells with KRAS mutation simultaneously." (PMID 38752985, 2024). "Circulating tumor DNA can thus be used as an alternative to EUS-FNB as a source from which to determine the patient prognosis based on various KRAS mutations." (PMID 39457426, 2024). "SEMA3Ahigh tumours were enriched for basal-like subtypes and major imbalances of the mutant KRAS allele." (PMID 38670629, 2024). "PDAC with oncogenic KRAS mutations alters the tumor microenvironment to promote tumor metastasis by releasing extracellular vesicles (EVs), a diverse group of bilayer membrane structures." (PMID 39488792, 2024). "KRAS mutations lead to sustained activation of the KRAS protein, enhancing tumor cell growth and spread." (PMID 38898987, 2024). "In vivo experiments showed that PKMYT1 KO markedly attenuated tumor growth although the tumors harbored oncogenic KRAS mutations." (PMID 38570712, 2024). "KRAS mutation has been reported to directly regulate the enzymatic activity of hexokinase 1, thereby increasing glucose utilization by tumor cells." (PMID 38384814, 2024). "The results of the production of IFN-γ showed that HLA-G12V/CD3 BiTE can only significantly activate T cells in the presence of KRAS G12V mutation tumor cells." (PMID 38752985, 2024). "In these models, the pancreas-specific expression of oncogenic KRAS is combined with the loss of a tumor suppressor to drive the formation of pancreatic intraepithelial neoplasia (PanIN) lesions and their progression to PC." (PMID 39518045, 2024). "Among the 803 patients with PDAC tested for somatic tumor mutations at MD Anderson, 703 were tested for KRAS mutations." (PMID 38310130, 2024). "In cases where clones of cells carrying activating KRAS mutations emerge in tumours that are resistant to anti‐EGFR therapies, it is notable that most of the cells in the tumour do not carry this mutation." (PMID 38887984, 2024). "KRAS mutations can lead to tumor-specific metabolic changes, thereby regulating oncogenic signaling networks and promoting tumor progression." (PMID 38397192, 2024).
tumor (continued). "For example, Kirsten rat sarcoma viral oncogene homolog (KRAS) activation leads to the production of pro-inflammatory cytokines recruiting neutrophils and tumor-associated macrophages, which have pro-tumor properties." (PMID 39764418, 2024). "Activating mutations in proto-oncogenes like KRAS are the initial events in the development of cancer followed by sequential progression involving additional genetic hits in tumour suppressor genes." (PMID 38168062, 2024). "Based on the KRAS mutation-derived estimates of tumor cellularity, roughly 14 of the 24 samples would be suitable for whole-exome sequencing, and only 3 of the samples would be ideal for whole-genome sequencing." (PMID 39123450, 2024). "The opposing relationships of BRAF and KRAS mutations with tumour infiltration of cytotoxic T cells was validated in an independent cohort of 608 CRC patients." (PMID 38040818, 2024). "This illustrates the need to consider both the KRAS mutation status and the tumor location when choosing a treatment regimen." (PMID 38790167, 2024). "A prospective study compared KRAS mutation results obtained from plasma cfDNA testing with those obtained from tumor tissue biopsy and showed that plasma cfDNA analysis exhibited 98% specificity and 92% sensitivity, with a concordance rate of 96%." (PMID 39064004, 2024). "KRAS-mutated tumours typically demonstrate an immunosuppressive TME, with secretion of immunosuppressive inflammatory cytokines, infiltration of immunosuppressive immune cells, and higher levels of PD-L1 expression." (PMID 39749035, 2024). "In 1994, a remarkable study identified tumor-associated KRAS and NRAS gene mutations in cfDNA, which sparked further curiosity to unravel the diagnostic and prognostic purposes of cfDNA in various tumors." (PMID 38770216, 2024). "KRAS-activating mutations have been detected in 5–57% of patients with iCCA, with a higher incidence often correlating with advanced tumor stages and poor prognosis." (PMID 39199659, 2024). "In the present study, inhibition of PKCδ in SW480 and HCT‐116 cells harboring a KRAS mutation indicated that it functions as a tumor promoter." (PMID 38425293, 2024). "In this study, we assessed the prognostic value of combining KRAS mutational status with tumor size in early-stage NSCLC." (PMID 38884086, 2024). "Positive PD-L1 staining (P = .0426) and tumor mutational burden elevation (P = .0264), as well as KRAS mutations, were more frequent in the LITT + ICB group, while tumors were more frequently driven by EGFR or ALK in the LITT-only group (P = .0021)." (PMID 39717437, 2024). "In the case of colorectal cancer (CRC), though a significant percentage of patients have KRAS mutations, the primary initiating event of neoplasm is mediated by either the loss of function of APC or mutation of β-catenin." (PMID 39056802, 2024). "At early stages of tumor progression, inflammatory macrophages are stimulated by KRAS‐mutated acinar cells to release proinflammatory cytokines, including TNF‐α and IL‐6." (PMID 38411356, 2024). "NCCN guidelines recommend the evaluation of tumor gene status, including KRAS/NRAS and BRAF mutations, as well as HER2 amplification and microsatellite instability (MSI)/mismatch repair (MMR) status, for the systemic treatment of advanced or mCRC45." (PMID 38172565, 2024).
tumor (continued). "In HCC, KRAS mutations are rare but its pathway can be activated via other mechanisms, contributing to tumour development and progression." (PMID 37944063, 2024). "It is recognized that activating KRAS mutations drives tumor initiation and progression in the vast majority of human PDAC; this process also requires a second major stimulus, such as inflammation." (PMID 38672675, 2024). "The absolute number of these immune cells infiltrated in TIME was analyzed, and results found that more NK cells in the stroma plus tumor region in the group of KRAS mutation than the wild type (WT)." (PMID 38292189, 2024). "Understanding the relationship between tumor location and KRAS mutations in the less-studied exon 4 is essential for improving the characterization of CRC patients." (PMID 37628934, 2023). "In fact, CDKN2A (encoding p16INK4A) exerts a far-reaching tumor-inhibition purpose by enhancing the KRAS signaling pathways activity in accelerating the malignant progression of cancer." (PMID 37390335, 2023). "As one of the most frequently mutated oncogenes in cancer, approximately 30% of all human cancers have Kirsten‐ras oncogene (KRAS) mutations, which have extensive effects on tumor transformation." (PMID 36994237, 2023). "THZ1 significantly inhibited the growth of xenograft tumour with KRAS‐G12V mutation, and the inhibition was markedly stronger than for KRAS‐G12D tumour." (PMID 38037549, 2023). "Then, the expression of the KRAS4A and KRAS4B cmRNA isoforms, together with KRAS mutational status and PD-L1 tumor expression by immunohistochemistry (IHC) were evaluated for their association with PD-L1 cmRNA level." (PMID 38030703, 2023). "The correlation between KRAS and some marker genes of immune cells, including tumor-associated macrophages (TAM), M2 macrophages, B cells, and T cells, was analyzed by TIMER." (PMID 38206735, 2023). "KRAS mutation can increase glucose uptake by regulating glucose transporters and glycolytic enzymes, which can enhance the Warburg effect in tumor cells." (PMID 36994237, 2023). "We also demonstrated that in YO, mortality hazards associated with KRAS sequence variation increased as tumor location became more distal." (PMID 38032636, 2023). "Although great progress has been achieved in targeting KRAS-mutant tumor antigens, this approach is limited to a subset of patients as the mutant KRAS peptide is only presented on specific HLA alleles." (PMID 37581538, 2023). "Here, we identified four factors, including ROS1 gene mutations, KRAS gene mutations, tumor staging, and a history of endocrine system diseases, which are associated with treatment efficacy in patients with PD-L1 positive expression." (PMID 37468609, 2023). "Since KRAS mutations occur in approximately 90% of PDACs, it makes even more sense to investigate the role of autophagy inhibitors in this type of tumor." (PMID 37894382, 2023). "WES revealed that both the original tumor and organoid had 19 somatic variants in common, including the KRAS p.G12D pathogenic variant." (PMID 36691316, 2023). "Several studies have also attempted to account for the fact that CTCs harbouring KRAS mutations are dissimilar to their matched primary tumours." (PMID 37761948, 2023). "We used the Cox proportional hazards regression method to investigate the effect of covariates such as age, sex, tumor location, metastatic spread, and KRAS mutation status on OS; we obtained an HR and 95% CI for each covariate." (PMID 36788889, 2023). "Molecular tumor testing revealed pathogenic mutations with low VAF in KRAS, ARID1A, BCORL1, and PRKDC." (PMID 37966258, 2023).